CTSO (cathepsin O)
Description:
Proteolytic enzyme possibly involved in normal cellular protein degradation and turnover.
Synonyms: CTSO1
Tractability: Antibody: UniProt predicts a signal peptide or a membrane-spanning region. PROTAC: ubiquitination databases record sites on it; its protein half-life has been measured.
Gene: Protein-coding gene on chromosome 4 (155,921,580 to 155,953,912, reverse strand). Ensembl gene ENSG00000256043.
Subcellular location: Lysosome
Pathways (Reactome):
Immune System: MHC class II antigen presentation
Gene Ontology:
Molecular function: protein binding; cysteine-type endopeptidase activity; cysteine-type peptidase activity
Biological process: proteolysis
Cellular component: lysosome
Genetic constraint (gnomAD): Loss-of-function variants: 27 observed, 24.71 expected, observed/expected ratio (o/e) 1.09, 90% interval 0.8 to 1.51. The upper end of that interval is the gene's LOEUF score, 1.51, which puts it in group 6 of 6, group 1 being the genes least tolerant of losing a copy. Missense variants: 325 observed, 260.1 expected, observed/expected ratio (o/e) 1.25, 90% interval 1.14 to 1.37. Synonymous variants: 122 observed, 100 expected, observed/expected ratio (o/e) 1.22, 90% interval 1.05 to 1.42.
Homologues: Orthologues: chimpanzee CTSO (99% identical), macaque CTSO (95% identical), dog CTSO (85% identical), pig CTSO (77% identical), rabbit CTSO (76% identical), rat Ctso (74% identical), guinea pig CTSO (73% identical), mouse Ctso (71% identical), tropical clawed frog ctso (54% identical), zebrafish ctso (51% identical), Caenorhabditis elegans R09F10.1 (26% identical), Caenorhabditis elegans Y51A2D.8 (24% identical), and 11 more. Paralogues in human: CTSF (30% identical), CTSL (29% identical), CTSV (29% identical), CTSH (28% identical), CTSK (28% identical), CTSS (28% identical), CTSW (28% identical), CTSC (25% identical), CTSZ (22% identical), TINAGL1 (20% identical), CTSB (19% identical), TINAG (19% identical).
Diseases named in the same sentence as CTSO in open-access papers:
CTSO is named in the same sentence as 30 diseases in open-access papers, as found by Europe PMC text mining. Sharing a sentence is not in itself a finding about the gene and the disease. The quoted sentences say what the papers report.
breast carcinoma (5 papers, 2017 to 2025). "It is also worth noting that breast cancer was associated with elevated CTSO, pharyngeal and endometrial cancers with elevated CTSS, ovarian cancer with decreased CTSZ, prostate cancer with decreased CTSS, and pancreatic cancer with decreased CTSE." (PMID 38883596, 2024). "Genetic factors, including SNPs in ZNF423 and cathepsin O (CTSO), influence susceptibility to ERα + breast cancer and response to SERM therapy, highlighting the potential for personalized medicine." (PMID 39736788, 2024). "Currently, only a limited number of studies have been conducted to examine the expression and role of cathepsin O in breast cancer." (PMID 36002710, 2023). "Since BRCA1 is important for deoxyribonucleic acid (DNA) double-strand break repair, the upregulation of cathepsin O contributes to the neoplastic transformation of breast cancer cells." (PMID 36002710, 2023). "Our previous GWAS using samples from the NSABP P-1 and P-2 selective estrogen receptor modulator (SERM) breast cancer prevention trials identified SNPs in ZNF423 and near CTSO that were associated with breast cancer risk during SERM chemoprevention." (PMID 28856246, 2017). "Nevertheless, these few studies show that cathepsin O is highly expressed by breast cancer cells." (PMID 36002710, 2023). "Its expression in ER-positive breast cancer cells suggests cathepsin O could be a suitable target for tumor imaging." (PMID 36002710, 2023). "In the present study, we identified additional SNPs that might contribute to inherited variation in SERM breast cancer prevention therapy by deep sequencing across CTSO and ZNF423 and subsequent functional genomic studies." (PMID 28856246, 2017). "However, cathepsin O expression and activity in tumor cells versus normal breast tissue, its cellular sources and localization should first be more extensively investigated for all breast cancer subtypes." (PMID 36002710, 2023). "Richard Weinshilboum from the Mayo Clinic in Rochester, Minnesota, USA, and colleagues previously showed that genetic variations in or near two genes—ZNF423 and CTSO—affected how well the drugs tamoxifen and raloxifene reduced the rate of breast cancer occurrence." (PMID 28856246, 2017).
glioma (2 papers, 2023). A benign or malignant brain and spinal cord tumor that arises from glial cells (astrocytes, oligodendrocytes, ependymal cells). "Thus, we performed quantitative real-time PCR (qRT-PCR) analyses, which confirmed that CTSH, CTSO, CTSF, CTSK, CTSS, CTSV and CTSB were significantly downregulated in glioma cells treated with ar-turmerone." (PMID 37768200, 2023).
liver steatosis (2 papers, 2023 to 2025). "Interestingly, we have recently reported the association of this marker and CTSO protein plasma levels, among other proteins, with liver steatosis in subjects with severe obesity due to the rare genetic disease Prader-Willi syndrome." (PMID 39017916, 2025).
Stroke (2 papers, 2024). Sudden impairment of blood flow to a part of the brain due to occlusion or rupture of an artery to the brain. "Our study is the first to explore at the genetic level the possibility that cathepsin O may increase the risk of stroke in the context of AF, although the connection to cathepsin O-mediated macrophage metabolism still requires confirmation through more detailed studies." (PMID 39027333, 2024). "The study also found a causal relationship between Cathepsin D and Parkinson’s disease, as well as between Cathepsin E and both stroke and multiple sclerosis, and between Cathepsin O and stroke." (PMID 39420987, 2024).
Arrhythmia (1 paper, 2025). Any cardiac rhythm other than the normal sinus rhythm. "Consequently, understanding the mechanistic contributions of cathepsin O to ECM remodeling and atrial fibrosis not only enhances our comprehension of AF pathogenesis but also highlights potential targets for intervention in this prevalent arrhythmia." (PMID 41169663, 2025).
basal cell carcinoma (1 paper, 2024). A carcinoma involving the basal cells. "In the MR study, we found that tissue protease L2 can promote skin cancer, Cathepsin O, and Cathepsin F are associated with an increased risk of basal cell carcinoma." (PMID 39312365, 2024).
ischemic stroke (1 paper, 2024). A stroke disorder caused by obstruction of blood flow to the brain, due to thrombotic (local blood clot formation) or embolic (due to a blood clot or other material traveling from another site) event. "Conversely, elevated levels of Cathepsin E (OR: 1.05, 95%CI: 1.01, 1.09, p = 0.015) and Cathepsin O (OR: 1.05, 95%CI: 1.01, 1.10, p = 0.021) were associated with an increased risk of ischemic stroke." (PMID 39420987, 2024). "Conversely, Cathepsin E and Cathepsin O were found to be risk factors for ischemic stroke." (PMID 39420987, 2024).
melanoma (1 paper, 2024). A malignant, usually aggressive tumor composed of atypical, neoplastic melanocytes. "In reverse Mendelian research, it was found that skin squamous cell carcinoma can increase the expression of Cathepsin H. Cathepsin E and Cathepsin O are also increased in melanoma and skin squamous cell carcinoma." (PMID 39312365, 2024). "In the reverse causal study, melanoma was found to cause an increase in cathepsin E (OR = 1.051, 95% CI: 1.011–1.093, P < .05), while CSCC was found to cause an increase in cathepsin H (OR = 1.154, 95% CI: 1.045–1.273, P < .05) and cathepsin O (OR = 1.111, 95% CI: 1.006–1.226, P < .05)." (PMID 39312365, 2024). "Cathepsin O showed independent promoting effects on BCC (OR = 1.137, 95% CI: 1.032–1.254, P < .05) and melanoma (OR = 1.165, 95% CI: 1.019–1.332, P < .05)." (PMID 39312365, 2024).
Obesity (1 paper, 2025). Accumulation of substantial excess body fat. "CTSO gene expression changes have been associated with microsome alterations in obesity in a transcriptome study, and increased plasma levels have been associated with the fat mass index (one of the best cardiometabolic disease risk predictors)." (PMID 39017916, 2025).
prostatitis (1 paper, 2024). An infectious or non-infectious inflammatory process affecting the prostate gland. "Our findings revealed that cathepsin O was beneficial in preventing BPH, whereas cathepsin X posed a potential threat to prostatitis." (PMID 38904040, 2024). "The examination of IVW MR findings showed that cathepsin O had a beneficial effect on BPH (IVW OR=0.94, 95% CI 0.89–0.98, P=0.0055), while cathepsin X posed a threat to prostatitis (IVW OR=1.08, 95% CI 1.00–1.16, P=0.047)." (PMID 38904040, 2024).
skin cancer (1 paper, 2024). "Reverse causal analysis suggests that squamous cell carcinoma may upregulate the expression of cathepsin O, indicating a complex interplay between these proteases and skin cancer development." (PMID 39312365, 2024).
squamous cell carcinoma (1 paper, 2024). A carcinoma arising from squamous epithelial cells. "In the reverse MR study, it was found that squamous cell carcinoma may cause an increase in Cathepsin O expression." (PMID 39312365, 2024).
steatosis (1 paper, 2025). Increased lipid within the cytoplasm of cells. "The study identified five circulating proteins associated with the steatosis grade in the liver: Cathepsin O (CTSO), Cadherin 2 (CDH2), Leukocyte immunoglobulin-like receptor subfamily A member 5 (LILRA5), and Serpin B6 (SERPINB6); and Prolyl endopeptidase (FAP)." (PMID 39017916, 2025). "The candidates to be combined in future algorithms for steatosis are CTSO, CDH2, LILRA5, SERPINB6, and FAP." (PMID 39017916, 2025). "Five circulating proteins, including Cathepsin O (CTSO), Cadherin 2 (CDH2), and Prolyl endopeptidase (FAP), were identified as biomarkers for steatosis." (PMID 39017916, 2025). "CDH2, CTSO, Leukocyte Immunoglobulin Like Receptor A5 (LILRA5), BMI, waist circumference, HOMA-IR, and FLI, among others, significantly correlated with the steatosis degree." (PMID 39017916, 2025). "Our results indicated that CTSO and FAP were affected not only by steatosis grade but also by the gender of the subject." (PMID 39017916, 2025). "Moreover, among the proteins showing changes in their expression with steatosis, we observed CDH2 (ρ = 0.52, p < 0.001), CTSO (ρ = 0.44, p < 0.001), and LLRA5 (ρ = 0.45, p < 0.001) presenting the most significant correlations." (PMID 39017916, 2025).
cancer (3 papers, 2018 to 2025). A tumor composed of atypical neoplastic, often pleomorphic cells that invade other tissues. "Other proteins with known liver/cancer associations such as cysteine cathepsin family member CTSO were also identified in our ZZ-HLC cells and may similarly provide prognostic and mechanistic insights into why individuals with A1ATD are at increased risk of tumourigenicity." (PMID 29879455, 2018). "In addition, the results showed a protective effect (OR = 0.93, 95% CI 0.88, 0.99, P = 0.019) of cathepsin O (CTSO) on ULs (all cancers excluded)." (PMID 39264885, 2024).
tumor (3 papers, 2022 to 2024). "Cathepsin O, on the other hand, is a type of cysteine protease that can be promoted by 20-hydroxyecdysone (20E) to enhance the immune response within the tumor." (PMID 39312365, 2024). "Interestingly, after PD-L1/CTLA-4 treatment, CTSO, MMP1, SPP1, and TPX2 were significantly up-regulated in tumor cells." (PMID 36225568, 2022).
digestive system tumors (1 paper, 2024). "This analysis encompassed a total of nine cathepsins include cathepsin B, cathepsin E, cathepsin F, cathepsin G, cathepsin H, cathepsin L2, cathepsin O, cathepsin S, and cathepsin Z, and six digestive system tumors (HCC, PCa, BTC, CRC, GC, and EC)." (PMID 38590662, 2024).
CTSO also shares sentences with these, for which no sentence is quoted: Cirrhosis (1 paper); diabetes (1); endometrial cancer (1); fibrosis (1); infection (1); lung carcinoma (1); multiple sclerosis (1); neurological diseases (1); ovarian carcinoma (1); pancreatic cancer (1); Parkinson disease (1); Prader-Willi syndrome (1); prostate carcinoma (1); skin squamous cell carcinoma (1).